CXCR4 (C-X-C motif chemokine receptor 4)
Diseases named in the same sentence as CXCR4 in open-access papers (continued):
Sharing a sentence is not in itself a finding about the gene and the disease.
metastatic disease (continued). "The high expression of this protein in A-72 suggests that the cell line originated from an aggressive cancer, indeed CXCR4 is known to be abundantly expressed in STS and is an independent predictor of poor prognosis and metastatic disease." (PMID 37038001, 2023). "In orthotopic primary and bone metastatic PCa models, treatment with the CXCR4 antagonist AMD3100 alone was ineffective, but when added to radiotherapy, it significantly inhibited metastatic tumor growth." (PMID 36831366, 2023). "Hence, we speculated that CXCR4 might be a sensitive marker for predicting metastatic diseases." (PMID 35729596, 2022). "CXCR4/SDF‐1 axis targeting has been demonstrated in several preclinical and clinical studies as a promising therapeutic strategy for metastatic disease in different cancers, including NSCLC." (PMID 34107168, 2021). "Many studies do not report the protein expression pattern; nevertheless in our study immunoreactivity to CXCR4 was observed mainly in the cell membrane while CXCL12 appears more often in the cytoplasm of primary and metastatic tumor cells." (PMID 30012106, 2018). "In addition, in order to rule out the possibility that the significant reduction of metastatic tumors in the shCXCR4 group was caused by the impact of CXCR4 on the tumor formation ability of ECSCs, we established a mouse subcutaneous tumor transplantation model." (PMID 28193907, 2017). "Expression of chemokines and their receptors, such as CXCL12/CXCR4 and CCL21/CCR7, in both primary and metastatic tumors suggest that chemokine receptor-bearing cells actively enter the circulation and home to metastatic sites." (PMID 25909600, 2015). "Expression of cortactin, CD44, NBS1, CXCR4, Snail and VEGF in patients with metastatic disease has been correlated to the development of distant metastases." (PMID 24212639, 2011). "Therefore, this work aims to elucidate the role of CXCR4 and its ligand in the progression of FMC and metastatic disease." (PMID 30012106, 2018). "Expression of the CXCR4 receptor, which is upregulated on cancer cells in both primary and metastatic tumors, mirrors that of CXCL12, suggesting that CXCR4-bearing cancer cells are actively guided by CXCL12 gradients to exit the primary tumor and metastasize to distant organs." (PMID 25909600, 2015). "A retrospective analysis by IHC of 30 patients with laryngeal and hypopharyngeal SCC showed a significant increase in CXCR4 expression in patients with positive lymph node and distant metastases compared to patients lacking metastatic disease." (PMID 24212639, 2011). "Although we previously observed a correlation between CXCR4 gene expression and disease extension/ metastatic disease at diagnosis (unpublished results), the current study does not shown any correlation between CXCR4 protein expression and occurrence of metastatic disease." (PMID 23249693, 2012). "CXCR4 expression was not correlated with occurrence of metastatic disease." (PMID 23249693, 2012).
non-Hodgkin lymphoma (54 papers, 2011 to 2025). Distinct from Hodgkin lymphoma both morphologically and biologically, non-Hodgkin lymphoma (NHL) is characterized by the absence of Reed-Sternberg cells, can occur at any age, and usually presents as a localized or generalized lymphadenopathy associated with fever and weight loss. "In the context of B-cell biology and disease, CXCR4 has been implicated in the migration and trafficking of malignant B cells in hematological malignancies, such as non-Hodgkin lymphoma and chronic lymphocytic leukemia." (PMID 39324141, 2024). "KARPAS299 is a human non-Hodgkin’s lymphoma T cell line that inherently expresses both CXCR4 and S1P1." (PMID 40012038, 2025). "Previous studies have proposed neutralizing CXCR4 as a therapeutic approach for non-Hodgkin’s lymphoma and have elucidated CXCR4-mediated cell migration in KARPAS299 cells." (PMID 40012038, 2025). "CXCR4 has an important role in the homing of progenitor cells to the bone marrow; thus, a blockade of CXCR4 is used when mobilization of cells to the periphery is desired (e.g., in some blood cancers like non-Hodgkin’s Lymphoma)." (PMID 38612911, 2024). "Among the four included articles, three described the use of 89Zr-labelled antibodies targeting CD20+ relapsed/refractory B-cell lymphomas and one concerned the use of 68Ga-labelled mAb targeting CXCR4 in patients with non-Hodgkin lymphomas." (PMID 35884548, 2022). "Failure rates have decreased since the CXCR4 antagonist plerixafor was approved for the mobilization of HSPCs for MM and non-Hodgkin lymphoma patients when given in conjunction with G-CSF133–135." (PMID 32025285, 2019). "In a cohort of 20 non-Hodgkin lymphoma patients, a significantly better prognosis and favorable treatment response was observed for patients experiencing a post-treatment decrease in CXCR4 expression in the bone marrow." (PMID 30774774, 2019). "The CXCR4 antagonist AMD3100 (Plerixafor) is clinically approved for the mobilization of hematopoietic stem cells (HSCs) for transplantation in patients with Non-Hodgkin's lymphoma (NHL) or MM." (PMID 30894861, 2019). "Recently, it was reported that non-Hodgkin lymphoma patients experiencing a decrease in bone marrow-expressed CXCR4 after treatment, responded well and had a significantly better prognosis." (PMID 27307990, 2016). "Our study demonstrated overexpression of CXCR4 in several types of non-Hodgkin lymphoma with [68Ga]pentixafor PET/CT, including lymphoplasmacytic lymphoma, marginal zone lymphoma, DLBCL, follicular lymphoma, mantle cell lymphoma, unclassified indolent B cell lymphoma, and EATL." (PMID 32757068, 2020). "The CXCR4 expression varies in different types of non-Hodgkin lymphoma." (PMID 32757068, 2020). "Additionally, plerixafor (also known as AMD3100), a CXCR4 antagonist, was approved for the mobilization of hematopoietic stem cells for transplantation in patients with non-Hodgkin’s lymphoma (NHL) or multiple myeloma (MM)." (PMID 31991604, 2020). "CXCR4 expression varies in different types of non-Hodgkin lymphoma." (PMID 32757068, 2020). "Also expression of CXCR4 was measured in peripheral blood and bone marrow of non-Hodgkin's lymphoma patients before and after treatment." (PMID 24859274, 2014). "The chemokine for CXCR4, stromal cell derived factor 1 (SDF1), has also been associated with HIV associated Non-Hodgkin's lymphoma (NHL) when individuals have a polymorphism in the SDF1 gene from G to A transition at position 801 (SDF1-3'A) that increased with homozygosity." (PMID 22420651, 2012). "In HIV-positive individuals at risk for developing non-Hodgkin lymphoma (pre-NHL), CD8+PD-1+CD27+CXCR4− T-cells positively correlate with CD4+FoxP3+PD-1+ T-cells expressing CD27, CD28, ICOS, and CD71." (PMID 41148820, 2025). "CXCR4 inhibition with AMD3100 and G-CSF supports stem cell mobilisation in Multiple Myeloma (MM) and non-Hodgkin lymphoma (NHL)." (PMID 40361472, 2025).
non-Hodgkin lymphoma (continued). "AMD3100 is the only marketed CXCL12/CXCR4 antagonist and was approved by the FDA in 2008 for autologous transplantation in patients with non-Hodgkin’s lymphoma (NHL) and multiple myeloma (MM)." (PMID 35893797, 2022). "Plerixafor (Mozobil), formerly known as AMD3100 (Genzyme, Cambridge, Mass, USA), is a CXCR4 antagonist which has been recently approved for PBSC mobilization in multiple myeloma (MM) and non-Hodgkin's lymphoma patients (NHL) undergoing ASCT." (PMID 22190942, 2011). "Plerixafor (AMD3100), a drug that targets CXCR4, is an effective mobilizer for HSC and used in the treatment of the patients suffering from multiple myeloma and non-Hodgkin lymphoma (NHL)." (PMID 35800881, 2022). "This has led to the approval of the CXCR4 antagonist plerixafor (AMD3100) as a hematopoietic precursor mobilisation agent, which releases HSCs into the peripheral blood for collection and subsequent autologous transplantation in Non-Hodgkin lymphoma (NHL) or MM patients." (PMID 34575965, 2021).
COVID-19 (53 papers, 2020 to 2026). A disease caused by infection with severe acute respiratory syndrome coronavirus 2. "The present findings suggest a potential protective role of the AA genotype and A allele of CXCR4 rs2228014 against severe COVID-19." (PMID 39407172, 2024). "More research on the underlying mechanisms via which mutations in the CXCR4 gene affect the severity of COVID-19." (PMID 39407172, 2024). "Examining the genetic variations in gene expression levels that might shed light on the ways in which COVID-19 severity is influenced by CXCR4 gene polymorphisms." (PMID 39407172, 2024). "Besides CTLA4, an increase in activated CXCR4 + T cells homing to the lungs is associated with fatal COVID-19." (PMID 36510222, 2022). "Interestingly, a similar observation was made in the BAL from patients with COVID-19, where most BAL infiltrates expressed CXCR3 and/or CXCR4, and the increased presence of activated lung-homing CXCR4+ T cells was associated with fatal COVID-19." (PMID 34803691, 2021). "CXCR4 is one of the most highly expressed basophil receptors in COVID-19 patients in our cohort and might be implicated in basophil transendothelial migration." (PMID 34548411, 2021). "CXCR4 is one of the most highly expressed basophil receptors in COVID-19 patients and might be implicated in basophil transendothelial migration." (PMID 34975885, 2021). "Moreover, the AA genotype and A allele of CXCR4 rs2228014 may confer protection against severe COVID-19." (PMID 39407172, 2024). "The mild COVID-19 group were overrepresented in population 0 (CD16+CD10+CD62L+CXCR2+CXCR4+) and population 7 (CD16+CD10+CD63+PD-L1hiLOX-1+CD62Llo)." (PMID 39253969, 2024). "In BAL fluids, elevated levels of CXCL12 in ICU patients with severe COVID-19 compared to ICU patients with influenza were observed, together with upregulation of CXCR4 on COVID-19 BAL fluid neutrophils." (PMID 36725964, 2023). "Among them, six genes (CXCR4, ENO1, FASN, GATA6, PDK1 and TUBB3) have been reported to be associated with the pathological mechanism of COVID-19 and OA." (PMID 37291167, 2023). "This expression can make T lymphocytes more susceptible to MIF signaling and to CD74-dependent activation, since also the signaling coreceptor molecules CXCR2 and CXCR4 were enhanced on T cells in COVID-19 patients." (PMID 37946732, 2023). "Genes related to T cell responsiveness such as IL21R, IL4R, CXCR4 were also upregulated in COVID-19-infected subjects." (PMID 36881624, 2023). "Therein, we suggested that the endothelial damage, caused by COVID-19, leads to impaired microcirculation, thrombogenesis and a reactive up-regulation of adhesion-molecules as well as activation of SDF-1/CXCR4 signaling." (PMID 35163504, 2022). "Expression of CXCR4 by neutrophils in patients with COVID-19 was already shown by single-cell RNA sequencing in the lungs." (PMID 34793331, 2022). "In fatal COVID-19 cases, the number of regulatory T cells and time-dependent escalation in activated CXCR4+ T cells was demonstrated." (PMID 35651623, 2022). "Mon HLA and Mon CD14 inside Delta samples differ in expression for the cytokine panel (CCL3, VEGFA, CCL5, CCL4, CXCR4, IL7R, CXCL8, and PF4) that have been found associated with COVID-19 severity and mortality." (PMID 36230912, 2022). "Surprisingly we found that the expression of chemokine receptor CXCR4, which promotes hematopoiesis, cell migration/homing and bone marrow retention, was reduced in different immune subsets from COVID-19 patients of our considered cohort." (PMID 34944610, 2021). "Immune cell profiling of COVID-19 patients in the recovery stage has shown high expression levels of the chemokine receptor CXCR4 in inflammatory monocytes, possibly indicative for fueling the inflammation during SARS-CoV-2-infection." (PMID 34054793, 2021). "Specifically, clusters associated with COVID-19 had higher expression of markers important for the activation and recruitment of basophils, including CD11b, CD63, and CXCR4." (PMID 34548411, 2021).
COVID-19 (continued). "GSVA analysis with COVID-19 vaccine RNA-seq data as the reference identified 1854 immune infiltration gene sets, with 200 associated with vaccination and 72 significant, including CD40 and CXCR4." (PMID 41232126, 2025). "The present study aimed to evaluate the association between the rs2228014 polymorphism in the CXCR4 gene and the severity of COVID-19, which, to our knowledge, has not been previously reported." (PMID 39407172, 2024). "The current study aimed to assess the association between the rs2228014 polymorphism in the CXCR4 gene and the severity of COVID-19, which has not been previously reported." (PMID 39407172, 2024). "For example, we observed a decrease in the CXCR2+CXCR4–CD62L+ mature-homeostatic neutrophils and an increase in CD16+CD10+CXCR2+CXCR4+CD62L+ aged neutrophils in patients with COVID-19, indicating a potential link between these subpopulations and disease severity." (PMID 39253969, 2024). "The expression of CXCR4 is upregulated in severely hypoxemic COVID-19 patients." (PMID 39407172, 2024). "It is thought that the expression of CXCR4, which is prevalent in COVID-19 patients, may serve as a prognostic indicator for ARDS and lung damage." (PMID 39407172, 2024). "In addition, CXCR4 signaling is considered as the key molecular regulator of different COVID-19 symptom including hypoxia and intussusceptive angiogenesis." (PMID 36949176, 2023). "Scientists has found that CXCR4 was highly expressed in COVID-19 patients." (PMID 37291167, 2023). "Transcripts of helper T cell markers CD4 and CXCR4, which is substantially elevated in patients with severe COVID-19, were both elevated, suggesting that CXCR4 activity may be less in bats compared to humans, or it may have a different role in bats." (PMID 37856551, 2023). "CXCR4 has been described as a neutrophil precursor marker and similarly it has been suggested that these immature neutrophils are being released into the blood during severe COVID-19." (PMID 35007290, 2022). "Interestingly, treatment of monocytes with the STAT-inhibitor and COVID-19 drug Ruxolitinib not only reduced the expression of STAT-targets CXCR4 and NAMPT, but also increased the expression of proinflammatory markers CXCL8 and CXCL2." (PMID 35998224, 2022). "Severe COVID-19 is characterized by enhanced activation of lung-homing CXCR4+ T cells, therefore, inhibiting their activity or translocation to the lungs may help reduce disease severity." (PMID 35651623, 2022). "Several genetic factors have been implicated in diverse responses to SARS-CoV-2 infection, such as the C-X-C chemokine receptor 4 (CXCR4) rs2228014 polymorphism, which has been previously studied in various diseases but has not been explored in the context of COVID-19 severity." (PMID 39407172, 2024). "In the COVID-19 dataset, CXCR4 (AUC:0.733), ENO1 (AUC:0.809), FASN (AUC:0.830), HIST1H4I (AUC:0.755), HIST1H4K (AUC:0.743), TUBA4A (AUC:0.811) and TUBB3 (AUC:0.814) exhibited relatively good diagnostic efficiency for distinguishing the patients with COVID-19 from healthy controls." (PMID 37291167, 2023). "However, since most naïve cells in COVID-19 patients gain this phenotype, we consider it unlikely that this is driven by antigen-specific memory development, but rather that CXCR4 may prime naïve T cells for trafficking to the lungs of COVID-19 patients." (PMID 36669118, 2023). "Previous studies showed an increase of inflammatory CXCR4+ T cells in the lungs of severe COVID-19 patients, supporting a hypothesis that lung-homing T cells contribute to immunopathology, and nonsuppressive T cells restrict pathogenesis and are involved in recovery from severe COVID-19." (PMID 36230912, 2022). "Furthermore, upon bacterial challenge, a similar pattern of cell surface receptor phenotype with reduced expression of CXCR1, CXCR2, CXCR3, CCR1, CCR5 and the maturation marker CD15, with increased expression of CXCR4 and CD66b was found in neutrophils from acute-phase COVID-19 patients." (PMID 35007290, 2022).
COVID-19 (continued). "Therefore, the up-regulation of CD62L, CD63, CD11b, and CXCR4 on basophils observed during the acute phase of COVID-19 and their normalization after viral clearance might imply a role of this phenotype in COVID-19 pathophysiology." (PMID 34548411, 2021). "Similarly, dysregulated TNF-α release results in apoptosis-promoting effects on highly activated effector T cells, and also increases the adhesion of lymphocytes in ALI by activating the SDF-1(CXCL12)/CXCR4 pathway, possibly also explaining decreased T cell counts (lymphopenia) in severe COVID-19." (PMID 33604758, 2021). "We observed that certain markers (CXCR4, CXCR2, CD63, and LOX-1) showed a correlation with COVID-19 disease severity." (PMID 39253969, 2024). "Population 1 (CD16+CD10+CD63hiCD62L–PD-L1–) was predominantly enriched in 1 healthy donor and virtually absent in others, whereas population 6 (CD16+CD10+CD62L+CXCR2+CXCR4–), which contained CD16+CD10+ cells, was underrepresented in COVID-19." (PMID 39253969, 2024). "By day three to five post-admission, we report increased levels of senescent CXCR4+ CXCR2- neutrophils, confirming a report of reduced CXCR2+ neutrophils in ICU COVID-19 patients." (PMID 36139476, 2022). "Further, chemokine and cytokine receptors (CXCR3, CXCR4, CXCR5, CCR4, CCR5, and CCR7) expression was increased in active COVID-19 and recovered patients." (PMID 36532041, 2022). "Specifically, in the COVID-19 patient’s B cells, we detected a substantial increase in the expression of CD52, CD74, CD22 and CD79B and a decrease in CXCR4, CD69, INFGR1, PTPRC and LAMP1 transcripts with respect to control-derived B cells." (PMID 34944610, 2021). "We also found an increased expression of CD63, ITGB2, CD37, CD2 and IL23R markers and the reduction in CXCR4, CD69, CD48, ICAM1 and S100A10 markers in COVID-19-derived NK-T cells compared to controls." (PMID 34944610, 2021). "Of interest, an altered expression of various receptors involved in migration, adhesion and activation, including CXCR4, CD63 and CD69, have been reported in COVID-19, highlighting specific immunophenotypes with predictive potential for clinical outcomes." (PMID 34944610, 2021). "PCA analysis recapitulated these differences, highlighting CD193, CD66b, CD11a, CD24, CXCR4, and CD62L as the most affected parameters in eosinophils from COVID-19 patients." (PMID 34548411, 2021). "The differences in marker expression on basophils between healthy controls and COVID-19 patients were further confirmed by PCA, with CXCR4, CD62L, CD193, and PD-L1 among the most contributing parameters driving the separation." (PMID 34548411, 2021). "The role of CXCR6, as well as of CCR5 and CXCR4, in MAIT cell recruitment in COVID-19, and in COVID-19 in general, is currently unclear and should be topics of future investigation." (PMID 32989174, 2020). "Additionally, stratification of the CXCR4+ T cells by CD4+ and CD8+ subsets showed that CD4+ T cell recruitment was much more abundant than CD8+ T cells, mirroring observations from COVID-19 lung infection studies." (PMID 41531734, 2026). "The heightened expression of CXCR4 and CD274 (PD-L1) in LDNs indicates a potential mechanism for immune evasion and persistent inflammation, adding a new dimension to the understanding of neutrophil heterogeneity in COVID-19." (PMID 39928675, 2025). "In order to determine which subpopulations of CD8+ T cells might be responsive to MIF during COVID-19, the expression of CXCR2 and CXCR4 on CD74+ CD8+ T cells was analyzed." (PMID 37946732, 2023). "The majority of CD74+ convCD4+ T cells at all stages of differentiation co-expressed the CXCR4 molecule, but increased frequencies of CXCR4+ CD74+ convCD4+ T cells in COVID-19 were only detected in cells with a naïve phenotype (mean: healthy 83.8%, mild: 82.1%, severe: 93.3%)." (PMID 37946732, 2023). "CXCR4 and PDK1 involved in the pathogenesis of both COVID-19 and OA." (PMID 37291167, 2023).